RNA5S7 (RNA, 5S ribosomal 7)
Synonyms: RN5S7
Gene: Ribosomal RNA gene on chromosome 1 (228,623,667 to 228,623,785, reverse strand). Ensembl gene ENSG00000202521.
Gene Ontology:
Molecular function: structural constituent of ribosome
Cellular component: ribosome
Homologues: Orthologues: guinea pig 5S_rRNA (100% identical), macaque 5S_rRNA (100% identical). Paralogues in human: RNA5S1 (100% identical), RNA5S10 (100% identical), RNA5S11 (100% identical), RNA5S12 (100% identical), RNA5S13 (100% identical), RNA5S14 (100% identical), RNA5S15 (100% identical), RNA5S16 (100% identical), RNA5S17 (100% identical), RNA5S2 (100% identical), RNA5S3 (100% identical), RNA5S4 (100% identical), and 26 more.